IL10 (interleukin 10)
Diseases named in the same sentence as IL10 in open-access papers (continued):
Sharing a sentence is not in itself a finding about the gene and the disease.
type 2 diabetes (106 papers, 2010 to 2025). "Both Treg and IL-10 have been associated with pathological angiogenesis, wound repair as reported in animal models of retinal neovascularization, left lung ischemia, type-2 diabetes, and airway allografts." (PMID 34069395, 2021). "CAD patients with MS and type 2 diabetes were treated with pioglitazone, and this therapy was associated with decreased IL-1β, IL-1Ra and IL-10 mRNA expression in EAT." (PMID 24684779, 2014). "Reduced IL-10 signaling has been associated with type 2 diabetes." (PMID 37313404, 2023). "Endurance exercise enhances the circulating levels of anti-inflammatory cytokines, such as interleukin-10 (IL-10) and interleukin-1 receptor antagonist (IL-1ra), and reduces pro-inflammatory conditions linked to type 2 diabetes, cardiovascular disease, and respiratory disease." (PMID 35185596, 2021). "Epidemiological and clinical studies have shown that coffee consumption may reduce the levels of pro-inflammatory biomarkers such as interleukin(IL)-1b, IL-4, IL-6, IL-10, and C-reactive proteins, which can contribute to a reduced risk of type 2 diabetes." (PMID 32722593, 2020). "Genetic polymorphisms in the TNF-α and IL-10 genes play a crucial role in the development of insulin resistance, type 2 diabetes mellitus (T2DM), and its complications." (PMID 39596058, 2024). "Twelve weeks of HIIT lower IL-6 and TNF-α in obese adolescents and type 2 diabetes patients, while enhancing IL-10 secretion to support anti-inflammatory capacity." (PMID 40777031, 2025). "Wang’s animal study stands alone in demonstrating the increased expression of pro-inflammatory cytokines TNF-α, IL-6 and IL-1β and the decreased expression of anti-inflammatory cytokines IL-4 and IL-10 in the midbrain of MPTP-treated type 2 diabetic mice." (PMID 40672460, 2025). "The goal of the research is to ascertain howTumour Necrosis Factor (TNFα), Type 2 diabetes has several etiopathogenic factors, including Interleukin-6 (IL-6), Interleukin-10(IL-10), and C - reactive protein (CRP)." (PMID 39132231, 2024). "Several studies have described either an increased expression of IL-10 in plasma of persons with type 2 diabetes or unchanged/reduced levels relative to healthy controls." (PMID 37313404, 2023). "We previously showed that interleukin-10 (IL-10) was upregulated in white adipose tissue (WAT) of obese women with type 2 diabetes (T2D)." (PMID 36313784, 2022). "The downregulation of IL-10 in db/db mice reflects significant immunological disturbances in these animals, as demonstrated in humans with Type 2 diabetes." (PMID 35330193, 2022). "A recent study, described that almost 20 circulating cytokines such as TNFα, IL-1a, IL-1b, GM-CSF, IL-10, IL-12, etc., are elevated in plasma of type 2 diabetic patients." (PMID 34202017, 2021). "It was shown that the increased production of IL-10 by MSCs inhibited Th17 differentiation, an important proinflammatory CD4+ T cell subtype that is associated with type 2 diabetes." (PMID 30356025, 2018). "Children who presented within 6 h of coma onset had higher concentrations of IL-1β, IL-6, and IL-10 than those who presented more than 18 h after coma onset." (PMID 30477519, 2018). "This study aims to assess the proinflammatory interleukin 1β (IL-1β) and anti-inflammatory IL-10 production by monocytes from 38 patients with type 2 diabetes and 31 controls in different glucose concentrations." (PMID 29225725, 2017). "It has been demonstrated that patients with type 2 diabetes have a reduced capacity for IL-10 production." (PMID 29225725, 2017). "We found that metformin reduced the levels of IL-6 in blood and MCP-1 in urine, but increased IL-10 levels in blood of patients with type 2 diabetes." (PMID 27904436, 2016). "In the present study, we determined the effects of metformin on the levels of pro-inflammatory cytokines (i.e., IL-6, TNF-α, and MCP-1) and anti-inflammatory mediator IL-10 in blood and urine of patients with type 2 diabetes." (PMID 27904436, 2016).
type 2 diabetes (continued). "In the present study, we determined the effects of metformin with different doses and durations on the levels of pro-inflammatory cytokines (i.e., IL-6, TNF-α, and MCP-1) and anti-inflammatory mediator IL-10 in blood and urine of patients with type 2 diabetes." (PMID 27904436, 2016). "IL-10 has a protective role in type 2 diabetes by increasing insulin sensitivity in skeletal muscle." (PMID 25302080, 2014). "MAS with coma/cerebral malaria were strongly associated with EMR1-rs373533 in Kumasi (p = 0.00019) and IL10-rs3024500 in the pooled analysis across the sites (p = 0.00064)." (PMID 23614351, 2013). "Others report that aerobic exercise training decreases plasma CRP, TNF-α and IL-18/IL-10 ratios in type 2 diabetics." (PMID 24324580, 2013). "Our findings indicated a significant difference between IL-10 serum levels in type 2 diabetic patients compared to healthy controls." (PMID 22737417, 2011). "Results of our study showed that the mean IL-10 serum level was 9.53±2.27 and 16.11±2.27 pg/ml in type 2 diabetic patients and control groups, respectively." (PMID 22737417, 2011). "In patients with Type 2 diabetes, black tea consumption was associated with increased regulatory T cells (CD3+ CD4+ CD25+ FOXP3) and immunosuppressive CD3+ CD4+ IL-10+ cells, alongside reduced proinflammatory CD3+ CD4+ IL-17+ cells and Th1-associated CD3+ CD4+ IFN-γ+ cells." (PMID 40008375, 2025). "In type 2 diabetic mice, IL-6 and IL-10 are key mediators of inflammatory responses." (PMID 40565702, 2025). "IL10 is an anti-inflammatory cytokine found at lower concentrations in type 2 diabetes." (PMID 36213511, 2022). "Evidence indicate that inflammation and, in particular, high levels of TNF-α, IL-β and IL-6 are factors involved in the development of type-1 diabetes, and TNF- α, IL-1, IL-6, IL-10, leptin, and adiponectin are the factors involved in the development of type-2 diabetes." (PMID 36011116, 2022). "In support of this hypothesis, we have reported resistance to IL-10’s anti-inflammatory action under hyperglycemic conditions in vitro and in individuals with type 2 diabetes (T2D)." (PMID 34234779, 2021). "In contrast, IL-10, an anti-inflammatory cytokine, is reduced in patients with type 2 diabetes." (PMID 27904436, 2016). "Individuals with type 2 diabetes had the most pronounced IL-6 and IL-10 elevations." (PMID 24555158, 2013). "Therefore, a longitudinal follow up study on obese children and adolescents is needed to clarify the role of IL10 in the progression of type 2 diabetes and MetS." (PMID 23941335, 2013). "Based on evidence suggesting that immune responses may be important in inducing type 2 diabetes, this study was designed to evaluate serum levels of IL-10 in type 2 diabetes." (PMID 22737417, 2011). "Aliakbari and colleagues showed that ASCs isolated from patients affected by type 2 diabetes displayed an increased pro-inflammatory character, with an upregulated expression of pro-inflammatory factors and a concomitant declined expression of IL-10 anti-inflammatory cytokine." (PMID 35327652, 2022). "Moreover, it appears that IL-10 may be an independent marker of disease in people with type 2 diabetes." (PMID 33114431, 2020). "Although the anti-inflammatory cytokines - IL-10 and TGF-β - have largely been associated with immune-regulation in LF (with IL-10 playing the major role), the down regulation of pro-inflammatory cytokines in type-2 diabetic subjects with LF seems to be due to TGF-β and not IL-10." (PMID 20559443, 2010). "The results of an investigation demonstrated astrong correlation between type 2 diabetics and TNFα, IL-6, CRP, and IL-10, receiving care at SMHS Hospital who is of Kashmiriorigin." (PMID 39132231, 2024). "In the remaining samples (healthy: 20; type 1 diabetes: 52; type 2 diabetes: 86), inflammatory cytokines were successfully measured in 99% (IL-6, TNF-α) and 100% (IL-8, IL-10, IFN-γ) of cases." (PMID 37189645, 2023).
type 2 diabetes (continued). "In a previous study with type-2 diabetic rats, treatment with an aqueous extract of Ajwa seed was shown to increase brain TGF-β1 and IL-10 levels." (PMID 36840284, 2023). "Therefore, this case–control study involving 327 cases (type 2 diabetes patients with proliferative DR (PDR)) and 461 controls (type 2 diabetes patients without DR) was conducted to address the relationship between IL-10 gene rs1800896 polymorphism and risk of PDR in Chinese population." (PMID 30890581, 2019). "There are specific effects on cytokines (serum IL-10 and urinary MCP-1) by the different durations and doses of metformin in patients with type 2 diabetes." (PMID 27904436, 2016). "Two clinical studies reported increased serum levels of anti-inflammatory cytokines (IL-4 and IL-10) and decreased levels of TNF-α, IFNγ, IL-12, and IL-6 in females with type 2 diabetes who received 8 weeks of daily NUTRIOSE® supplementation (10 g/day) versus baseline levels." (PMID 37836513, 2023). "The paradoxical enrichment of the IL-10 pathway in our study may suggest resistance to IL-10′s anti-inflammatory actions in ME/CFS females, as was shown in individuals with Type 2 diabetes." (PMID 37373402, 2023). "Visceral white adipose tissue (abdomen and upper body) appears to be the major source of inflammatory markers in type 2 diabetes (cytokines, TNF-alpha, IL-1, IL-6, IL-10, leptin, adiponectin, monocyte chemoattractant protein, angiotensinogen, resistin, chemokines, etc.)." (PMID 37298118, 2023). "The model of Type 2 diabetes in db/db mice is characterized by increased expression of TNF-α in the spleen, underexpression of IL-10 in the liver and spleen, an elevated number of PMNs in peripheral blood (a sign of inflammation), and diminished expression of chitinases in the liver and spleen." (PMID 35330193, 2022). "In a Dutch study, IL-10 capacity, measured as IL-10 levels after stimulus with lipopolysaccharide (LPS), was negatively associated with levels of glucose, HbA1c and LDL, as well as risk of type 2 diabetes, but not with BMI." (PMID 35135482, 2022). "All of the pro-inflammatory cytokines evaluated (IL-1β, IL-6, IL-8, IL-10, IL-12p70, and TNF-α) were increased in patients with type 2 diabetes, although only the increases in TNF-α, IL-8, and IL-12 p70 were statistically significant in comparison to healthy individuals (P < 0.05)." (PMID 22500980, 2012). "As IL-26 induces the secretion of active IL-1-beta (without affecting IL-1RA and IL-10 production), its involvement in sterile auto-inflammatory disorders (such as type II diabetes) should be investigated." (PMID 23055831, 2012). "Participants with type 2 diabetes who consumed oleocanthal-enriched HP-EVOO experienced enhanced antiplatelet effects, lower inflammatory cytokine levels (TNF-α, IL-1β, and IL-6, p < 0.05) and enhanced anti-inflammatory IL-10 concentration (p = 0.032) compared to butter, olive oil and EVOO groups." (PMID 40136590, 2025). "IM patients with type 2 diabetes (main group) have a 2.7 times increase in CRP content, 4.4 and 3.1 times in proinflammatory IL-6 and TNF-α, respectively, as well as anti-inflammatory IL-10 concentration of 1.9 times higher relative to the indicators in the control group." (PMID 32341698, 2020).
type 2 diabetes (continued). "Thus, according to the results of our research, taking ALA for 4 months in patients with type 2 diabetes who underwent non-Q-MI reduced the activity of systemic inflammation and did not significantly affect the content of anti-inflammatory IL-10 in these patients." (PMID 32341698, 2020). "According to the results of our research, taking alpha-lipoic acid for 4 months in patients with type 2 diabetes who underwent non-Q-myocardial infarction reduced the activity of systemic inflammation and did not significantly affect the content of anti-inflammatory IL-10 in patients." (PMID 32341698, 2020).
experimental autoimmune encephalomyelitis (104 papers, 2009 to 2026). An autoimmune demyelinating disease of the central nervous system that is produced experimentally in animals by the injection of homogenized brain or spinal cord in Freund's adjuvant. "Induction of a more tolerogenic gut DC phenotype and increases in IL-10 and IL-13 by manipulation of gut microbiota are associated with attenuation of subsequently induced experimental autoimmune encephalomyelitis." (PMID 24147013, 2013). "Furthermore, LPS-treated Tmod1-deficient DCs secreted high levels of IFN-β and IL-10, and induced immune tolerance in an experimental autoimmune encephalomyelitis (EAE) mouse model." (PMID 33552047, 2020). "Furthermore, Tmod1-deficient mDCs secreted high levels of IFN-β and IL-10 and induced immune tolerance in an experimental autoimmune encephalomyelitis (EAE) mouse model." (PMID 33552047, 2020). "The same study also identified that overexpression of let‐7e induces activation of Th1 and Th17 cells, exacerbating experimental autoimmune encephalomyelitis by targeting IL‐10." (PMID 40323732, 2025). "In a previous study, CXCL12 promoted the differentiation of Tregs and increased IL-10 expression in an experimental autoimmune encephalomyelitis model by TCR-stimulated human T cells." (PMID 40309773, 2025). "There is mounting evidence that combining MSCs and IL10 protein therapy can reduce inflammation in a variety of diseases, including experimental autoimmune encephalomyelitis, spinal cord injury and ischemia–reperfusion injury." (PMID 41181974, 2025). "In line with this, in experimental autoimmune encephalomyelitis (EAE), a murine demyelinating and paralyzing model of MS in IL-10-deficient animals develop a more severe disease, while IL-10-overexpressing mice are highly resistant to EAE." (PMID 40332510, 2025). "A role of IL-10 in the pathogenesis of MS has been consistently evidenced in experimental studies based on animal models of MS (i.e., experimental autoimmune encephalomyelitis, EAE), and in humans." (PMID 38585351, 2024). "The fact that CD138hi plasma cells are the major source of IL-35+ and IL-10+ B cells have been highlighted in mice model of Experimental Autoimmune Encephalomyelitis (EAE) and Salmonella infection." (PMID 36067164, 2022). "Using an IL-10 reporter mouse system, Matsumoto and colleagues have shown that mainly plasmablasts expressed IL-10 in a model of experimental autoimmune encephalomyelitis (EAE) and that removal of these cells exacerbated the disease." (PMID 34293057, 2021). "In the CNS, IL-10 is mainly produced by astrocytes and microglia and it is upregulated after various insults, such as experimental autoimmune encephalomyelitis, middle cerebral artery occlusion, excitotoxicity, and traumatic brain injury." (PMID 32611425, 2020). "IL-10 knockout (KO) mice are protected from experimental autoimmune encephalomyelitis (EAE) with low-dose estrogen (E2) treatment similar to wild-type (WT) mice." (PMID 31665042, 2019). "When applied with appropriate localization, amounts, and timing, IL-10 can completely protect animals from experimental autoimmune encephalomyelitis (EAE)." (PMID 31244763, 2019). "For example, CXCL12 polarizes CXCR4+ macrophages into IL-10-secreting M2-like macrophages and CXCR4+CD4+ T cells into IL-10-producing regulatory T cells (Tr1) that suppress experimental autoimmune encephalomyelitis (EAE)." (PMID 30320116, 2018). "A variety of regulatory B cell (Breg) subsets have been identified, interleukin-10 (IL-10)-producing Bregs in a murine model of experimental autoimmune encephalomyelitis (EAE), in humans and TGF-β1 producing B cells when stimulated with LPS in vitro." (PMID 30083152, 2018). "Mice with B cell-specific deletion of Hif1a have reduced number of IL-10-producing B cells, which result in exacerbated collagen-induced arthritis and experimental autoimmune encephalomyelitis." (PMID 29343683, 2018).